CTLA4 (cytotoxic T-lymphocyte associated protein 4)
Diseases named in the same sentence as CTLA4 in open-access papers (continued):
Sharing a sentence is not in itself a finding about the gene and the disease.
tumor (continued). "By targeting both PD-1/PD-L1 and CTLA-4, it is possible to address different activation and inhibition mechanisms in T cells, further enhancing the anti-tumor immune response." (PMID 39308869, 2024). "The use of ICIs to block PD-1/PD-L1 and CTLA-4/CD80/86 signaling pathways enhances the efficient immune responses against cancer cells, revitalizing tumor antigen recognition and causing tumor death." (PMID 39409094, 2024). "Overall, the evidence suggested an enhanced tumor infiltration by T cells following the combination of 16 Gy + anti-CTLA4." (PMID 39199612, 2024). "Meanwhile, The CD8+ T cells within reaction to the stimulation by the DC/tumor fusion vaccine as well as CTLA-4 blocker activation enhanced survival and cytotoxicity." (PMID 38824143, 2024). "Other significant associations included low muscle type with increased CTLA4 and decreased pan-AKT expression in tumor epithelium, and high adiposity with increased CD3, CD8, CD20, and CD45RO expression in stroma (p < 0.05; false discovery rate > 0.2)." (PMID 39769193, 2024). "Third, it was found that CC and CT genotypes of the CTLA-4 c.-1765C>T SNV were more common in patients under 54 years of age, suggesting that they predispose individuals to early occurrence of the tumor." (PMID 39596391, 2024). "Monoclonal antibodies targeting PD-1/PD-L1 and CTLA-4 have proven to be valuable tools for overcoming the inhibitory regulation of T-cell activation imposed by tumor cells or the tumor microenvironment (TME)." (PMID 39539894, 2024). "Current approved ICI in clinic relies on the re-activation of anti-tumor CD8+ T cells by neutralizing co-inhibitory molecules CTLA4 and/or PD1/PD-L11–4." (PMID 38242867, 2024). "PD-1/PD-L1 inhibitors and CTLA-4 inhibitors are among the most advanced targets in tumor immune checkpoint therapy, operating at different stages of the immune response." (PMID 39068460, 2024). "Immune checkpoint blockade is a cutting-edge cancer immunotherapy that targets molecules like CTLA-4 and PD-1 to activate T cells and boost anti-tumor immunity." (PMID 39161771, 2024). "Another study using POL loaded with CTLA-4 checkpoint inhibitor also demonstrated reduction of antibody levels and slowed down tumor growth." (PMID 38858467, 2024). "Blocking CTLA-4 mAb can lead to a surge in T cell proliferation and their subsequent attack on tumor cells." (PMID 38835341, 2024). "Convincing evidence indicates that tumours make use of immune checkpoints, such as PD-1, PD-L1, and CTLA-4, to evade the immune response." (PMID 38503865, 2024). "Stable Tregs promote the death of Th2 cells by CTLA-4 expression and competing for IL-2, which plays a crucial role in inhibiting Th2 cells from promoting tumor growth and metastasis." (PMID 38509593, 2024). "We previously showed that combining anti-CTLA-4 with cDCV therapy increased cDCV efficacy against a subcutaneous tumor over and above that seen with either anti-CTLA-4 or cDCV alone." (PMID 39409873, 2024). "There is often mutual regulation among immune checkpoints in the TIME, which prompted us to further evaluate the PD-1, PD-L1, and CTLA4 protein levels in the tumor tissues using IHC after anti-CD47 Ab treatment." (PMID 38398223, 2024). "Based on the anti-tumor immunity, immune checkpoint blocking therapy, including anti PD-1, anti PD-L1 and anti CTLA-4 shows great efficacy on a large amount of solid tumors." (PMID 38189855, 2024). "Numerous studies have demonstrated that CTLA-4 therapies deplete tumor resident Treg cells and downregulate cytotoxic T-cell activity." (PMID 38956700, 2024). "Most studies do not consider the possible immunoregulatory impact of the soluble form of CTLA-4 even though it is evident that blocking CTLA-4 can trigger anti-tumor immunity by promoting the infiltration of cytotoxic effector T cells into tumors." (PMID 38053333, 2024).
tumor (continued). "Programed death-1, programmed death-ligand 1 (PD-1, PD-L1), and cytotoxic T-lymphocyte antigen-4 (CTLA-4) are immune checkpoint molecules that protect tumor cells from immune attack." (PMID 38646528, 2024). "Nanostring analysis of tumour tissues five days post-LDRT revealed an upregulation of genes encoding PD-1 and CTLA-4 expressed by exhausted T cells, the regulatory T cell marker FOXP3, and the myeloid stimulatory receptor CD40." (PMID 38833685, 2024). "Studies have shown that combined treatment with anti-CTLA-4 and anti-PD-1 increases the number of TLSs and B cells, leading to tumor regression." (PMID 39840050, 2024). "Entinostat (ENT; Class I HDAC inhibitor) has shown significant efficacy in tumor immunotherapy when combined with anti-PD-1/anti-CTLA-4 antibodies, functioning by reducing the number of tumor-infiltrating G-MDSCs." (PMID 39620228, 2024). "Although the advent of PD1/PDL-1 and CTLA-4 inhibitors has transformed the landscape of treatment for many tumours, to date, ICIs have been unsuccessful in PDAC, with trials reporting disappointing outcomes." (PMID 39330013, 2024). "mCTLA-4 is frequently upregulated in tumours, rendering it a prominent subject of investigation in CTLA-4 studies and correlating it with aggressive cancer." (PMID 38893123, 2024). "The intricate relationship between CTLA-4 and T cell function as well as the tumor microenvironment emphasizes how intricate immune regulation is in cancer treatment." (PMID 38931856, 2024). "Tregs promote tumor growth by inhibiting the role of tumor immune cells through a variety of means; a large body of evidence suggests that Tregs expressing CTLA-4 are responsible for the inhibitory effect on conventional T cells." (PMID 39329710, 2024). "Numerous preclinical models have consistently demonstrated that ICIs targeting CTLA-4 and PD-1/PD-L1 can restore the recognition and eradication of tumor cells by T cells." (PMID 39068460, 2024). "Initially, ICIs were considered to exert their effect merely by reactivation and proliferation of “predysfunctional” CTLs present in the tumor microenvironment (TME) upon inhibition of the interaction between CTLA4/PD-1 and their ligands." (PMID 38541099, 2024). "Its similarity to CD28, but opposing function, highlights the B7/CTLA-4 checkpoint as a critical target for tumor-specific T-cell activation." (PMID 38342925, 2024). "This transition towards an inhibited state is likely as a result of chronic stimulation, mirroring T cells whereby continuous tumour antigen stimulation leads to increased expression of the inhibitory receptors PD-1 and CTLA-4 and functional exhaustion." (PMID 38745765, 2024). "HLA-G can inhibit many players associated with the anti-tumor response throughout early and late tumor stages, although CTLA-4 and PD-1 are predominantly expressed in higher tumor grades." (PMID 38450191, 2024). "Clinical data suggest that treatment with anti–CTLA-4 and anti–PD-1 antibodies alters and diversifies the TCR repertoire within the tumor microenvironment and is positively associated with antitumor responses." (PMID 39436696, 2024). "The interaction between CTLA-4 and B7 is a critical checkpoint that, when blocked, reshapes the immune response and demonstrates sustained anti-tumor effects in specific cancer subpopulations." (PMID 38473398, 2024). "To this end, in the same E.G7-OVA tumor model, we compared the anti-tumor effects of NC, CTLA4 KO, CUL5 KO and CTLA4/CUL5 double KO (DKO) OT-I T cells post adoptive transfer." (PMID 38242867, 2024). "OC patients with low risk score had a higher PD1&CTLA4 immunophenoscore, higher TMB score, lower TIDE score and lower tumor escape score, suggesting a better immunotherapy response." (PMID 38461331, 2024). "In the context of cancer, the upregulation of CTLA-4 can contribute to immune escape mechanisms, allowing tumor cells to evade immune surveillance and promoting tumor growth and progression." (PMID 39769153, 2024).
tumor (continued). "The results demonstrated a positive correlation between FANCD2 and immune checkpoints in most tumor tissues, including CTLA4, HAVCR2, LAG3, PDCD1, PDCD1LG2, SIGLEC15, TIGIT, and particularly CD274." (PMID 38443946, 2024). "MPO deficiency significantly reduced CD11b+Ly6G+ myeloid cells, macrophages and exhausted CD4+PD1+CTLA4+ T cells within the tumor microenvironment." (PMID 38367056, 2024). "With the tumor environment related to the outcome of immune checkpoint inhibitor treatments, our study found that low-risk patients demonstrated higher levels of CTLA-4, PD-1, and PD-L1, suggesting that immunotherapies targeting these entities could be more beneficial for such patients." (PMID 38347041, 2024). "In the tumor microenvironment, ICBs block the co-inhibitory receptors of T cells, such as PD-1 and CTLA-4, and inhibit the inhibitory signals of antigen-specific T cells, enabling them to attack tumor cells more effectively." (PMID 38672120, 2024). "In both T3 and F244 tumour models, the respective HDVax-induced cluster 3 cells expressed higher levels of CTLA4 protein than cells in all other clusters, except cluster 5 (classical CD25+ Treg cells)." (PMID 39048822, 2024). "It has been shown that in a clinical setting, the use of these inhibiting anti-CTLA-4 antibodies is able to enhance the activity of effector T cells while suppressing regulatory T cells, resulting in net inhibition of tumor progression." (PMID 38893120, 2024). "As expected, improved CD8+ cytotoxic T cells and suppressed Tregs in CD4+ T cells were observed in PLGA-R837@Cat with CTLA-4 antibody-treated tumor tissues compared to other groups." (PMID 39769944, 2024). "Ipilimumab is an anti-CTLA-4 inhibitor that expands the range of available tumor immunotherapy approaches, in contrast to the widespread use of single-drug PD-1/PD-L1 inhibitors in the field of tumor therapy." (PMID 38898003, 2024). "CD4+ cells, which had infiltrated into the tumor following anti-CTLA-4 Ab administration, showed a significant decrease in infiltration ability when combined with the IFN-g neutralizing Ab." (PMID 39106430, 2024). "Upon establishing the binding specificity of AYA22T-R2-13 to CTLA-4 on cytotoxic T lymphocytes (CTLs), our investigation aimed to uncover its potential in enhancing CTL-mediated tumor cell lysis by disrupting CTLA-4 interactions with the CD80 or CD86 axis." (PMID 38473398, 2024). "Meanwhile, The CD8+ T cells in response to the activation of the DC/tumor fusion vaccine and CTLA-4 blocker activation enhanced survival and cytotoxicity." (PMID 38824143, 2024). "Based on these findings, alternative drugs can be considered in place of anti-CTLA-4 monoclonal antibodies, in combination with anti-PD1, to downregulate irAEs associated with IBD and potentially enhance the anti-tumor effects." (PMID 39456702, 2024). "Compared to MSS tumors, the tumor microenvironment of dMMR/MSI-H CRC shows a significant upregulation of immune checkpoints like PD-L1, CTLA-4, LAG-3, and IDO, which generate tumor-associated immunogenic antigens." (PMID 39839672, 2024). "Mice treated with neoAg SLP vax in combination with anti-CTLA-4 or anti-PD-1 displayed enhanced tumor control compared to control vax + anti-PD-1 or control vax + anti-CTLA-4." (PMID 39446585, 2024). "Immune checkpoint inhibitor therapy is a form of cancer treatment that blocks receptors and their ligands, such as PD-1, PD-L1, and CTLA-4, which regulate immune responses, thereby enhancing the ability of T cells to recognize and attack tumor cells." (PMID 39273009, 2024). "In both immunograms of all patients and chemotherapy patients specifically, glycolysis and recognition of tumor cells exhibited the highest scores, while immune checkpoints and anti-CTLA4 resistance MAGE gene (CRMA) signature demonstrated the lowest." (PMID 39335178, 2024).
tumor (continued). "For example, ipilimumab has been shown to be a promising immunotherapeutic drug that blocks CTLA-4 and enhances the anti-tumor immune response in advanced melanoma." (PMID 39343796, 2024). "Within this investigation, we demonstrate that the synergistic effects of anti-CD47 and CTLA4 blockade in immunotherapy yield an efficient anti-tumor impact on NSCLC." (PMID 38398223, 2024). "For B7-H3, its immunomodulatory role suggests potential synergy with immune checkpoint inhibitors, such as anti-PD-1 or anti-CTLA4 therapies, to overcome immune resistance and enhance anti-tumor immunity." (PMID 39766159, 2024). "Tumors co-opt immune checkpoint proteins such as CTLA-4 to create an immunosuppressive tumor microenvironment (TME), circumvent immune surveillance, and promote tumor progression." (PMID 38956700, 2024). "Tregs utilize CTLA-4 to suppress effector T cell activity in the tumor microenvironment, facilitating tumor immune escape." (PMID 39770433, 2024). "Among the eight treatment groups, APG‐157 + anti‐CTLA‐4 demonstrated the best tumor growth suppression (p = 0.0065 compared to the control), followed by anti‐PD‐1 + anti‐CTLA‐4 treatment group (p = 0.48 compared to the control)." (PMID 38686626, 2024). "Dietary consumption of EPS derived from Lactobacillus delbrueckii, EPS-R1, sensitized Colon26 and 4T1 tumors to anti-CTLA4 blockade therapy, significantly reducing tumor progression." (PMID 38200347, 2024). "Considering the factors that contributed to the favorable outcome of the combination of CTLA-4 in this study, it is possible that the anti-tumor immune responses were activated because all patients were post-irradiation." (PMID 38611087, 2024). "Although PD-1 or CTLA-4 expression and its significance in the tumor microenvironment have been investigated in HCC patients, most previous studies focused on the isolation of specific immune cells." (PMID 38672574, 2024). "In mouse models, RCT001 enhanced the efficacy of anti-CTLA4 + anti-PD1 by inhibiting tumor-associated M2 macrophages and tumor-associated neutrophils." (PMID 38504270, 2024). "Anti-tumor immune drugs (ipilimumab) targeting CTLA4 can, therefore, markedly improve the prognosis of patients with advanced tumors." (PMID 38552216, 2024). "tested the effects of IL-21 in combination with monoclonal antibodies (mAbs) for CTLA-4 and PD-1 regulatory receptors after tumor establishment in several mouse models." (PMID 38638431, 2024). "In comparison to singular treatments with lycorine hydrochloride and anti-CTLA-4, the combination therapy exhibited better tumor inhibition effects." (PMID 39245716, 2024). "We observed a high expression of CTLA-4 in tumor cells in all patients with the immune-high subtype and in four of the six cases with immune-low subtype, although at significantly lower levels than in the immune-high subtype." (PMID 38611048, 2024). "For instance, targeting the cytotoxic T-lymphocyte-associated protein 4 (CTLA-4) molecule promotes T cell activation and cytotoxicity, thereby inhibiting tumor growth and metastasis." (PMID 39136027, 2024). "High-ANXA2 was correlated with decreased proportion of granzyme B+ CD8+ T cells (Spearman’s ρ = − 0.40, P = 0.01), and increased TIM-3+ (Spearman’s ρ = 0.43, P < 0.001) and CTLA4+ (Spearman’s ρ = 0.49, P < 0.001) tumor-infiltrating lymphocytes." (PMID 38519766, 2024). "This suggests that, following anti-CTLA4 treatment, Treg cells can continue to proliferate and limit the anti-tumor immune response." (PMID 38927907, 2024). "In a preclinical study, the researchers discovered that the coadministration of intratumoral G47Δ and systemic anti-CTLA-4 antibody effectively mobilized effector T cells into the tumor, concurrently reducing regulatory T cells." (PMID 38725667, 2024).
tumor (continued). "These monoclonal antibodies, blocking immune checkpoint-relevant molecules such as PD1, PD-L1, and CTLA-4, exert their effect by inhibiting the immunosuppressive signals in T cells, thus amplifying T cell-mediated tumor cytotoxicity." (PMID 38523155, 2024). "Excitingly, in mouse lung and melanoma models, SB-3CT, a small-molecule MMP2/9 inhibitor, has been shown to enhance PD-1 or CTLA-4 blockade responses by promoting anti-tumour immunity." (PMID 38791926, 2024). "CTLA-4 blockade has been shown to enhance RT-induced tumor regression in mouse models and clinical studies." (PMID 38349740, 2024). "Nowadays, advancements in immune checkpoint inhibitors (ICIs) therapy (anti-CTLA-4 and anti-PD-1 monoclonal antibodies) have reduced tumor recurrence rates and, therefore, improved OS in patients with ARM." (PMID 39697934, 2024). "During tumor immunity, Tregs suppress excessive immune responses and promote immune escape of tumor cells by expressing inhibitory factors such as CTLA4, IL-10, and TGF-β." (PMID 38745661, 2024). "Similar to the PD-1/PD-L1 pathway, cancer cells can exploit the CTLA-4 pathway to evade immune destruction by upregulating the expression of B7 ligands or expressing soluble CTLA-4, thus suppressing T cell activity and promoting tumor immune evasion." (PMID 39308869, 2024). "The Fc-enhanced modification of the CTLA-4 antibody increases T cell priming within the tumor microenvironment and elicits a strong response." (PMID 39335494, 2024). "The potential of recombinant adeno‐associated (rAAV) and oncolytic vaccinia virus to selectively target PD‐1 and CTLA‐4‐based therapy to the tumour site shows promise in preclinical evaluations." (PMID 38963257, 2024). "CTLA-4 is a crucial immune checkpoint receptor involved in the maintenance of immune homeostasis, tolerance, and tumor control." (PMID 38053333, 2024). "ICIs, by blocking the PD1-PD-L1 and the CD86/CTLA4 axes, prevent tumor cells from releasing wrong messages to T cells, thereby restoring tumor-induced immuno-deficiency in TIME." (PMID 39007147, 2024). "As a result, the combination therapy showed better tumor control compared to using radiation and anti-PD-1 alone Moreover, this regimen increased the presence of Tregs and engaged the CTLA-4 axis within the TME." (PMID 39629128, 2024). "Analysis of intratumoral TILs (iTILs) within the cancer cell nests using HALO software showed that administration of the anti-CTLA-4 Ab significantly increased the infiltration of CD4+ T cells into the tumor." (PMID 39106430, 2024). "The first approved therapy in targeting such immune resistance was ipilimumab, which inhibits CTLA-4 and increases generic and tumour-specific T-cell activation." (PMID 38893071, 2024). "Mice were administered either the increased ω-3/ω-6 ratio diet or a control diet for 12 d, at which point they were inoculated with B16F10 tumor cells and subsequently treated with systemic anti-CTLA4 once tumors were established." (PMID 38330013, 2024). "Tumor cells that secrete VEGF upregulate immune-suppressive molecules such as CTLA4, LAG3, and TIM3." (PMID 38540240, 2024). "In summary, the expression of PD-1, CTLA-4, LAG-3, TIM-3, and TIGIT ligands in tumor cells is associated with an adverse prognosis." (PMID 38893211, 2024). "IL-18 engineered to avoid decoy-receptor binding enhances tumor rejection by anti-CTLA-4 in kidney cancer models through immune microenvironment remodeling." (PMID 39561007, 2024). "The combination of radiation with immune checkpoint inhibitors, such as anti-PD-1 or anti-CTLA-4 therapies, has been shown to enhance the abscopal response by overcoming the immunosuppressive tumor microenvironment often present in metastatic disease." (PMID 39770433, 2024). "The experimental data from this investigation confirm that the combined targeting of CD47 and CTLA4 enhances immunity against solid tumors in LLC cell-transplanted tumor-bearing mice." (PMID 38398223, 2024).